MIR4300 (microRNA 4300)
Synonyms: hsa-mir-4300
Gene: MicroRNA gene on chromosome 11 (81,890,741 to 81,890,836, reverse strand). Ensembl gene ENSG00000264110.
Diseases named in the same sentence as MIR4300 in open-access papers:
MIR4300 is named in the same sentence as 2 diseases in open-access papers, as found by Europe PMC text mining. Sharing a sentence is not in itself a finding about the gene and the disease. The quoted sentences say what the papers report.
idiopathic scoliosis (1 paper, 2021). A scoliosis with no known cause. "Considering histochemical and physiological abnormalities in muscles of patients with idiopathic scoliosis, we suggested that CRTC1 may be the target gene of MIR4300 that may function in the curve progression." (PMID 33985553, 2021).
MIR4300 also shares sentences with these, for which no sentence is quoted: adolescent idiopathic scoliosis (1 paper).